CYP27B1 (cytochrome P450 family 27 subfamily B member 1)
Diseases named in the same sentence as CYP27B1 in open-access papers (continued):
Sharing a sentence is not in itself a finding about the gene and the disease.
COVID-19 (7 papers, 2020 to 2023). A disease caused by infection with severe acute respiratory syndrome coronavirus 2. "The dominant mode of inheritance of rs10877012 polymorphism of CYP27B1 gene reported increased association of the T allele with asymptomatic COVID-19 with OR = 2.51 (1.05–5.99)." (PMID 36833234, 2023). "In the current project, we have appraised expression levels of VDR, CYP27B1 and a number of associated lncRNAs in the circulation of COVID-19 patients versus healthy subjects using real-time PCR method." (PMID 34147082, 2021). "It has been demonstrated that enzyme 25(OH)D 1-α hydroxylase (CYP27B1) is upregulated in activated immune cells, so circulating 25(OH)D levels could be lowered by the COVID-19-associated systemic inflammatory response." (PMID 37035323, 2023). "In the current project, we have appraised expression levels of VDR, CYP27B1 and mentioned lncRNAs in the circulation of COVID-19 patients versus healthy subjects to unravel the role of these transcripts in the pathogenic processes during the course of COVID-19." (PMID 34147082, 2021).
osteoporosis (7 papers, 2016 to 2025). A condition of reduced bone mass, with decreased cortical thickness and a decrease in the number and size of the trabeculae of cancellous bone (but normal chemical composition), resulting in increased fracture incidence. "The importance of the vitamin D-endo/para/autocrine system is further confirmed by the correlation between T1D development, osteoporosis, and the presence of functionally defective alleles in Cyp27b1 and Vdr genes." (PMID 29552033, 2018). "Our previous data showed that disruption of Cyp27b1 gene in mice induced premature aging associated with multiple defects such as growth retardation, osteoporosis, hypophosphatemia, skin atrophy, temporomandibular joint (TMJ) osteoarthritis(OA), etc." (PMID 26790152, 2016). "Genetic variations or single‐nucleotide polymorphisms (SNPs) in CYP27B1 and CYP24A1 have been associated with susceptibility to osteoporosis, as they modulate vitamin D availability and calcium signalling." (PMID 40831018, 2025). "However, the impacts of carrying only one pathogenic allele of the CYP27B1 c.262delG variant is currently unknown but could be important for prevention of osteoporosis and other vitamin D deficiency associated conditions in regions with high prevalence of these disorders such as the SLSJ." (PMID 41574189, 2025). "The imbalance of VDRs and CYP27B1 in bone tissue from diabetic rats found in this study may reflect the changed ratio of osteoblasts to osteoclasts with a shift to the formation of active osteoclasts, which can cause bone resorption and lead to the development of secondary osteoporosis." (PMID 29552033, 2018). "Previous studies have shown that Cyp27b1-/- mice displayed premature aging including growth retardation, osteoporosis, TMJ-OA, etc." (PMID 26790152, 2016). "As an observation, the significant effects of ELD that were noted even in Cyp27b1+/+ mice indicated that ELD can promote Ca absorption and improve osteogenesis in patients with osteoporosis." (PMID 30281599, 2018). "The multifactorial pathogenesis of osteoporosis involves complex interactions between genetic factors and vitamin D metabolism, particularly involving key genes such as the vitamin D receptor (VDR), CYP27B1 and CYP24A1." (PMID 40831018, 2025). "Furthermore, AR could upregulate the expression of CYP27B1 and decrease the expression of CYP24A1, which indirectly increased the synthesis of VD in vivo, promoted osteogenesis, and alleviated the symptoms of osteoporosis." (PMID 34304712, 2021).
type 1 diabetes (7 papers, 2012 to 2023). "Alternatively, polymorphisms in CYP27B1, also associated with type 1 diabetes may have a role in regulating vitamin D 1-alpha hydroxylation in a tissue-specific manner." (PMID 24614117, 2014). "In the kidney, 1-α-hydroxylase, encoded by CYP27B1 converts 25-hydroxyvitamin D3 to 1,25-dihydroxyvitamin D, directly affecting the circulating levels of active vitamin D. Polymorphisms within CYP27B1 have previously been associated with the development of type 1 diabetes." (PMID 28754147, 2017). "For example, SNPs in NAD synthetase 1/ 7-dehydrocholesterol reductase (NADSYN1/DHCR7) gene locus and SNPs in CYP27B1, CYP2R1 genes and have been associated with type 1 diabetes or with type 1 diabetes related autoantibodies." (PMID 28976992, 2017). "Genetic studies of type 1 diabetes pinpointed susceptibility single nucleotide polymorphisms (SNPs) mapped to genes in the vitamin D metabolism milieu, namely synthesis (DHCR7) and hydroxylation (CYP2R1, CYP27B1)." (PMID 37170809, 2023). "In 612 infants, we genotyped single nucleotide polymorphisms in vitamin D metabolism genes that relate with type 1 diabetes: rs10741657 and rs12794714 in CYP2R1, rs12785878 in DHCR7, and rs10877012 in CYP27B1." (PMID 37170809, 2023).
autoimmune disease (6 papers, 2012 to 2025). A disorder resulting from loss of function or tissue destruction of an organ or multiple organs, arising from humoral or cellular immune responses of the individual to their own tissue constituents. "The polymorphism C/A of the promotor CYP27B1 (21260) seems to be linked to endocrinal autoimmune diseases." (PMID 36313775, 2022). "A significant link has been found between allelic variation of the promotor (21260) C/apolimorphism and AD, concluding therefore that the polymorphism C/A of the promotor CYP27B1 (21260) seems to be linked to endocrinal autoimmune diseases." (PMID 36313775, 2022). "CYP27B1 is expressed in macrophages, dendritic, T and B cells and CYP27B1-1260 promoter polymorphism (rs10877012) has been reported to influence the levels of 1,25[OH]2D in serum and associated with HBV infection and autoimmune diseases in adults." (PMID 34226633, 2021).
breast tumors (6 papers, 2010 to 2024). "Based on these genomic data, expression of the genes that encode VDR, CYP27B1, and CYP24A1 appears to be in the normal range for the vast majority of breast tumors." (PMID 34950835, 2021). "A later study also reported that AKT phosphorylation, integrin expression, and activation of STAT3 signaling pathways were upregulated after CYP27B1 ablation in breast tumors." (PMID 33163485, 2020). "In contrast, a recent paper has demonstrated that CYP27B1 mRNA in breast tumours is decreased in comparison with normal mammary tissue." (PMID 20831823, 2010). "It has been observed that both CYP27B1 and CYP24A1 are up-regulated in breast tumours when compared with normal tissue." (PMID 20831823, 2010). "Conversely, we have also demonstrated that COX-2 expression is higher in breast tumors with elevated expression of CYP24A1, an enzyme responsible for VD3 catabolizing, whereas tumors with high CYP27B1 expression (enzyme responsible for VD3 synthesis) exhibit lower COX-2 expression." (PMID 38355711, 2024).
Hypertension (6 papers, 2017 to 2025). The presence of chronic increased pressure in the systemic arterial system. "In the context of hypertension, an SNP in CYP27B1 was associated with congestive HF (odds ratio: 2.14 for subjects homozygous for the C allele; 95% CI: 1.05–4.39)." (PMID 28827564, 2017). "Briefly, the kidney cells responsible for renin production (juxtaglomerular cells) are sensitive to calcitriol, and VDR and CYP27B1 knock-out mice develop high renin systemic hypertension which can be rescued with angiotensin converting inhibitors." (PMID 40448712, 2025). "A stepwise regression model was established comprising gender, age, visceral obesity, ALT, γ-GT, hypertriglyceridemia, hypertension, low HDL-C, hyperglycemia, and combined unfavorable alleles (CYP24A1 rs2296241-A, CYP24A1 rs2248359-T, and CYP27B1 rs4646536-T)." (PMID 34484304, 2021). "Recent research conducted with mice without the Vdrgene (which codes for the vitamin D receptor) and the Cyp27B1 gene (which codes for alpha-1-hydroxylase) demonstrated thatthese animals had high levels of renin and, consequently, of angiotensin II,provoking hypertension and cardiac hypertrophy." (PMID 34178073, 2020).
lymphoma (6 papers, 2018 to 2025). A malignant (clonal) proliferation of B- lymphocytes or T- lymphocytes which involves the lymph nodes, bone marrow and/or extranodal sites. "We next selected the CYP27B1 locus, which is involved in granulomatous disease and tumors such as lymphomas, to construct a model of TAD fusion-mediated chromosomal looping and gene transcription activation." (PMID 39394698, 2024). "The methylation level of CYP27B1 is elevated in primary lymphoma and leukemia cells." (PMID 30208925, 2018).
secondary hyperparathyroidism (6 papers, 2017 to 2025). Overproduction of parathyroid hormone in response to influence external to the parathyroid glands. "This elevation is due to 2 phenomena: (a) inactivation of the CYP27B1 enzyme — thus, no conversion — and, more importantly, (b) secondary hyperparathyroidism that suppresses the activity and expression of the Cyp24a1 gene and CYP24A1 enzyme." (PMID 38916957, 2024).
tuberculosis (6 papers, 2010 to 2025). A chronic, recurrent infection caused by the bacterium Mycobacterium tuberculosis. "Furthermore, we found that CYP27B1 activity in monocytes is higher among patients with active tuberculosis than those with frequent TB contact." (PMID 24371450, 2013). "Using an ex vivo bioassay, in this study, we found that 1-α hydroxylase (CYP27B1) activity in monocytes is significantly higher in patients with active tuberculosis (TB) than in those with frequent TB contact." (PMID 24371450, 2013). "In future studies, the levels of CYP27B1 and CYP24 and the metabolites of vitamin D3, such as calcitroic acid and 24,25(OH)2D3, should be quantified to clarify vitamin D3 metabolism in the pathophysiological process of tuberculosis." (PMID 24371450, 2013).
Autoimmunity (5 papers, 2020 to 2023). The occurrence of an immune reaction against the organism's own cells or tissues. "As previously shown, the genetic polymorphism of CYP27B1 associated with autoimmunity causes a relative resistance to vitamin D requiring a higher level of circulating 25(OH)D3 to achieve biologically active 1,25(OH)2D3, resulting in normalized immune functions." (PMID 35458137, 2022). "The study also found no direct correlation between miRNAs and T1DM-related auto-antibodies but discovered a negative association between CYP27B1 mRNA levels and IA-2 autoantibodies, indicating a potential role of the CYP27B1 gene in T1DM autoimmunity." (PMID 37888206, 2023).
cervical cancer (5 papers, 2023 to 2025). A primary or metastatic malignant neoplasm involving the cervix. "In summary, CYP27B1 may regulate cell health by activating 25(OH)D3 precursor to 1,25(OH)D3 in healthy cervical tissue and cervical cancer." (PMID 36979850, 2023). "In addition, we have reported that CYP27B1 expression and activity are detected in SiHa cervical cancer cells, which correlated with local calcitriol production from its precursor 25OHD3." (PMID 37240017, 2023). "Therefore, precursors of vitamin D hormone may function as a chemotherapeutic in cervical cancer mediated by autocrine CYP27B1 activation." (PMID 36979850, 2023). "This is also in agreement with the effect on cervical cancer cells SiHa and HeLa wherein enhanced VDR expression and activity were observed along with the CYP27A1 and CYP27B1 gene upregulation up on treatment with calcitriol." (PMID 40920750, 2025). "Cervical cancer cells express an autocrine vitamin D metabolising system (VDMS) comprised of a vitamin D receptor, vitamin D catabolic enzyme (CYP24A1), and the activating enzyme of 25-hydroxycholecalciferol (25(OH)D3), CYP27B1." (PMID 36979850, 2023). "Studies in HeLa cervical cancer cells demonstrated that calcitriol increased the gene expression of both CYP27A1 and CYP24A1, without affecting CYP27B1, whose mRNA was reduced by 25OHD3." (PMID 37240017, 2023).
chronic kidney disease (5 papers, 2021 to 2024). Impairment of the renal function secondary to chronic kidney damage persisting for three or more months. "The levels of 1,25(OH)2D are also decreased in patients with very severe 25(OH)D deficiency, those with chronic renal insufficiency or in rare cases of CYP27B1 mutations (vitamin D-resistant rickets type 1A)." (PMID 33815294, 2021). "Finally, in a podocyte injury model of chronic kidney disease–mineral bone disorder (CKD-MBD), SIK inhibitor treatment stimulated renal Cyp27b1 expression and 1,25-vitamin D production." (PMID 36862513, 2023).
non-small cell lung carcinoma (5 papers, 2016 to 2023). A group of at least three distinct histological types of lung cancer, including non-small cell squamous cell carcinoma, adenocarcinoma, and large cell carcinoma. "Significant associations between CYP27B1 expression or gene polymorphisms and cancer risk were found, for example, for colorectal, ovarian, and non-small cell lung cancer." (PMID 36362448, 2022). "More recently, the same authors, with similar approach identified 7 SNPs in 6 genes (CYP27B1, MAT1A1, CHST1, CYP4B1, ADH6, and SLC22A1) associated with the occurrence of skin rash in advanced non-small cell lung cancer treated with erlotinib." (PMID 27304055, 2016).
alopecia (4 papers, 2012 to 2026). Hair loss usually from the scalp. "Phenotypic differences between Cyp27b1-deficient and Vdr-deficient mice and humans (e.g., alopecia in the latter only) have been documented and attributed to 1,25D-independent functions of the Vdr." (PMID 39321290, 2024). "This distinction is critically illustrated by comparing VDR‐null mice, which develop complete alopecia after the first hair cycle, with CYP27B1‐null mice, which lack the enzyme to produce active vitamin D but maintain functional VDR and exhibit normal hair cycling." (PMID 41473843, 2026). "CYP27B1−/− mice do not have alopecia, but their keratinocytes exhibit reduced expression of differentiation markers and have an inhibited ability to recover normal skin barrier function after an acute perturbation." (PMID 23049920, 2012). "The stark phenotypic difference between VDR‐null mice (which develop alopecia) and CYP27B1‐null mice (which maintain normal hair despite lacking active vitamin D) underscores that many critical VDR actions in hair follicles operate independently of ligand binding." (PMID 41473843, 2026).
cardiac hypertrophy (4 papers, 2014 to 2021). "Cyp27b1–/– mice have vitamin D metabolism disorders and developed hypertension, cardiac hypertrophy, and cardiac contractile dysfunction." (PMID 33981701, 2021). "Electrocardiogram and cardiac contractility analysis revealed higher, sharper R waves and worsened myocardial contractile rhythm in Cyp27b1–/–mice and HF mice than in control animals, suggesting that VD could alleviate cardiac hypertrophy and improve cardiac function." (PMID 33981701, 2021). "VDR but also CYP27B1 KO mice have high BP levels and cardiac hypertrophy due to increased activation of the renin-angiotensin system (RAS), and calcitriol treatment inhibits renin activation and decreases BP and cardiac hypertrophy in CYP27B1 KO mice." (PMID 25376735, 2014).
Chronic Hepatitis C (4 papers, 2012 to 2017). "The allele frequencies of the gene polymorphic loci studied were similar in patients with chronic hepatitis C and controls; the only exception was represented by the G allele of CYP27B1 rs10877012 G>T found to be slightly more frequent in control subjects than in patients." (PMID 24244713, 2013). "Previous studies showed that genetic variation of the vitamin D metabolic pathway, including CYP27B1-1260 rs10877012 and VDR FokI rs2228570, was associated with sustained virological response to PegIFN therapy in patients with chronic hepatitis C infection." (PMID 28296915, 2017). "Logistic regression analysis of demographic, biochemical and virological variables at baseline and of CYP27B1, VDR and IL28B gene polymorphisms in relation with the lack of response (failure to antiviral therapy) in 238 patients with chronic hepatitis C." (PMID 24073221, 2013). "Single functional nucleotide polymorphisms of genes of CYP2R1, GC and CYP27B1 are known to influence the vitamin D serum levels but it is still unknown if they could have a clinical significance in influencing the success of antiviral therapy of chronic hepatitis C." (PMID 24244713, 2013). "The results of the present genetic validation study suggest, in line with our previously published findings, an association between the CYP27B1-1260 promoter SNP rs10877012 and SVR to treatment of chronic hepatitis C with PEG-IFN-α and ribavirin." (PMID 22808108, 2012).
hyperparathyroidism (4 papers, 2018 to 2024). Hyperfunction of the parathyroid glands resulting in the overproduction of parathyroid hormone. "In a previous study, when 1α,25D3 was administered to Cyp27b1–/–mice, hyperparathyroidism was improved." (PMID 30281599, 2018).
hyperphosphataemia (4 papers, 2011 to 2025). "FGF23 mutationsassociated with FTC cause hyperphosphataemia through effects on expression of thesodium-phosphate co-transporter in the kidney and small intestine, and throughincreased activation of vitamin D due to increased renal expression of CYP27B1(25-hydroxyvitamin-D 1 alpha hydroxylase)." (PMID 21533022, 2011).
Insulin resistance (4 papers, 2019 to 2025). Increased resistance towards insulin, that is, diminished effectiveness of insulin in reducing blood glucose levels. "This raises the tantalizing possibility of other underlying mechanisms, perhaps genetic polymorphism or insulin resistance, playing a role in modulating CYP27B1 expression." (PMID 37888206, 2023). "The finding that none of the investigated miRNA correlated with CYP27B1 mRNA levels suggests that other mechanisms (e.g., those related to insulin resistance) must be responsible for the decreased CYP27B1 expression in the adipose tissue in obese subjects." (PMID 31652924, 2019). "Additionally, while CYP27B1, responsible for synthesizing the active form of vitamin D3, was down-regulated in the insulin resistance group, its expression normalized in TQ-treated groups." (PMID 39906623, 2025).